ACTG2 (actin gamma 2, smooth muscle)
Description:
Actins are highly conserved proteins that are involved in various types of cell motility and are ubiquitously expressed in all eukaryotic cells.
Synonyms: ACTA3; ACTL3; ACTSG; ACT; ACTE; MMIHS5; VSCM; VSCM1
Tractability: Small molecule: a structure with a bound ligand is known. PROTAC: ubiquitination databases record sites on it.
Chemical probes: BISTRAMIDE A (high quality)
Gene: Protein-coding gene on chromosome 2 (73,892,232 to 73,919,865, forward strand). Ensembl gene ENSG00000163017.
Subcellular location: Cytoplasm, cytoskeleton
Pathways (Reactome):
Cell-Cell communication: Activation of STAT3 by cadherin engagement; Regulation of CDH1 Function
Extracellular matrix organization: Formation of the dystrophin-glycoprotein complex (DGC)
Muscle contraction: Smooth Muscle Contraction
Gene Ontology:
Molecular function: ATP hydrolysis activity; structural constituent of cytoskeleton
Biological process: mesenchyme migration; positive regulation of gene expression; cellular response to acetaldehyde; cellular response to interleukin-6; cytoskeleton organization; response to ethanol
Cellular component: blood microparticle; extracellular exosome; extracellular region; actin cytoskeleton; cell body; cytoplasm; cytosol; filopodium; lamellipodium; myosin filament; cell periphery; cytoskeleton
Genetic constraint (gnomAD): Loss-of-function variants: 16 observed, 38.85 expected, observed/expected ratio (o/e) 0.41, 90% interval 0.28 to 0.63. The upper end of that interval is the gene's LOEUF score, 0.63, which puts it in group 2 of 6, group 1 being the genes least tolerant of losing a copy. Missense variants: 238 observed, 506.37 expected, observed/expected ratio (o/e) 0.47, 90% interval 0.42 to 0.52. Synonymous variants: 181 observed, 185.07 expected, observed/expected ratio (o/e) 0.98, 90% interval 0.87 to 1.11.
Homologues: Orthologues: dog ACTG2 (100% identical), guinea pig ACTG2 (100% identical), macaque ACTG2 (100% identical), mouse Actg2 (100% identical), pig ACTG2 (100% identical), rabbit ACTG2 (100% identical), rat Actg2 (100% identical), chimpanzee ACTG2 (95% identical). Paralogues in human: ACTA2 (99% identical), ACTC1 (99% identical), ACTA1 (98% identical), ACTG1 (94% identical), ACTB (93% identical), ACTBL2 (88% identical), ACTR1B (54% identical), ACTR1A (53% identical), ACTRT3 (49% identical), ACTRT2 (48% identical), ACTR2 (47% identical), ACTRT1 (47% identical), and 14 more.
Diseases named in the same sentence as ACTG2 in open-access papers:
ACTG2 is named in the same sentence as 52 diseases in open-access papers, as found by Europe PMC text mining. Sharing a sentence is not in itself a finding about the gene and the disease. The quoted sentences say what the papers report.
Megacystis (10 papers, 2014 to 2025). Dilatation of the bladder postnatally. "While megacystis and (sub)ileus episodes, as an expression of intestinal hypoperistalsis, were present in all ACTG2 variants and individuals, other features significantly varied between specific variants." (PMID 41387873, 2025). "Mutations in ACTG2 are associated with genitourinary phenotypes like hydroureter, megacystis and undescended testes (OMIM #619431)." (PMID 41249932, 2025). "Megacystis-Microcolon-Intestinal Hypoperistalsis Syndrome has five types caused by MYLK, MYH11, LMOD1, MYL9, and ACTG2 genes and has unknown prevalence." (PMID 39480826, 2024). "Genetic testing was performed to rule out megacystis-microcolon syndrome, but specific ACTG2 and MYH11 mutations were not tested due to the limited availability of comprehensive genetic panels, which we recommend for future cases to better characterize the underlying pathophysiology." (PMID 41149692, 2025).
visceral myopathy (10 papers, 2014 to 2025). "Visceral myopathy, primarily due to ACTG2 gene mutations (ACTG2-related myopathy), presents with varying phenotypes, including MMIHS, chronic intestinal pseudo-obstruction, and multisystemic smooth muscle dysfunction syndrome (MSMDS)." (PMID 40539155, 2025). "Of note, in patients with ACTG2 variants other than P39 or R40 mutations cholecystolithiasis was significantly more likely suggesting a cumulative effect of PN and visceral myopathy in MMIHS cholelithiasis." (PMID 41387873, 2025). "Genetic mutations in ACTG2, particularly recurrent arginine substitutions, have been identified as the primary cause of visceral myopathy, influencing disease severity and burden." (PMID 40539155, 2025). "Similar impairment of esophageal motility was described in pediatric and adult patients with visceral myopathy associated with ACTG2 gene mutations." (PMID 40860336, 2025). "We recommend a nomenclature change to ‘autosomal dominant ACTG2 visceral myopathy’ for patients with pathogenic variants in ACTG2 and associated VM phenotypes." (PMID 37288276, 2023). "In our VM cohort, ACTG2 mutations were the leading cause of VM, and we recommend a nomenclature change to autosomal dominant ACTG2 visceral myopathy for such cases." (PMID 37288276, 2023). "In a large study, the rate of molecular diagnosis in visceral myopathy cases was 64%, of which 97% was due to ACTG2 variants." (PMID 36551277, 2022). "Nonetheless, ACTG2-associated visceral myopathy typically leads to prolonged hospitalization, repeated surgery, nutritional deficiencies, and serious complications from intravenous nutrition." (PMID 32814715, 2020). "Heterozygous point mutations in actin γ 2, smooth muscle (ACTG2) are the primary cause of visceral myopathy." (PMID 32814715, 2020). "Actin γ 2, smooth muscle (ACTG2) R257C mutation is the most common genetic cause of visceral myopathy." (PMID 32814715, 2020). "Aside from ACTG2, other genes underlying visceral myopathies have been described." (PMID 37288276, 2023). "ACTG2 mutations are the most common cause of visceral myopathy." (PMID 32814715, 2020). "It is not well understood how ACTG2 mutations cause visceral myopathy." (PMID 32814715, 2020). "Additionally adult onset visceral myopathy was recently associated with a dominant mutation in the ACTG2 enteric actin gene in a Finnish family." (PMID 24676022, 2014). "This suggests variable expressivity in MMIHS, possibly warranting classification under the broader ACTG2-related visceral myopathy spectrum." (PMID 40539155, 2025). "In 2020, Hashmi and co-workers suggested that in visceral myopathy, ACTG2 plays roles in functions that may depend on the submembranous actin network, namely, cell spreading and cell migration." (PMID 40971055, 2025). "A mutation associated with visceral myopathy profoundly disrupts actin gamma 2, smooth muscle (ACTG2) filament bundles without changing the global actin cytoskeleton in visceral smooth muscle cells." (PMID 32814715, 2020). "This is supported by the recent identification of a recessive mutation in a premature stop codon of LMOD1 as a cause of a rare congenital visceral myopathy, MMIHS, which usually arises due to autosomal dominant mutations in the smooth muscle enriched actin gamma 2 (ACTG2) gene." (PMID 30444878, 2018).
breast carcinoma (4 papers, 2009 to 2025). "Similar to PNET and breast cancer, both drugs induce vascular pMLC and ACTG2 expression resulting in enhanced tumor perfusion and reduction of hypoxia (Fig. EV4B–E)." (PMID 40140727, 2025). "MiR-145 is often deregulated in cancer cells and is known to induce ACTG2 expression in breast cancer." (PMID 27107594, 2016). "An expression microarray analysis performed on a derivate breast cancer cell line resistant to cisplatin showed that ACTG2 expression increases in the chemotherapy resistant cell line compared to the normal indicating that it may be associated with cisplatin resistance." (PMID 20043850, 2009).
chronic intestinal pseudo-obstruction (4 papers, 2017 to 2025). "However, individuals with ACTG2 genetic variants are usually identified early in life, with severe chronic intestinal pseudo obstruction." (PMID 34805998, 2021).
osteosarcoma (3 papers, 2015 to 2022). A usually aggressive malignant bone-forming mesenchymal neoplasm, predominantly affecting adolescents and young adults. "The expression levels of RASGRP2 and KCNJ3 were upregulated in osteosarcoma cells, while the expression of ACTG2 was decreased." (PMID 36686667, 2022). "In contrast, ACTG2 was down-regulated in osteosarcoma groups." (PMID 36686667, 2022). "In addition, the differential expression of ACTG2 may play an essential role in the development of osteosarcoma." (PMID 36686667, 2022). "However, few data are available regarding a role for γSMA in cancer cells: It has been reported that ACTG2 encoding for γSMA is one of the two most up-regulated genes in highly aggressive osteosarcoma cell lines when compared to non-aggressive cell lines." (PMID 26110787, 2015). "Among them, the expression of MYH6 and SULT4A1 in osteosarcoma was higher than that in control group, while the expression of LIPE, ACTG2, KLF4, and TF was decreased." (PMID 34104648, 2021).
Berdon syndrome (2 papers, 2021 to 2025). "MMIHS, also known as Berdon syndrome, is a congenital disorder often caused by mutations in the ACTG2 gene, which encodes gamma-actin, a key protein involved in smooth muscle function." (PMID 40539155, 2025). "Heterozygous de novo missense mutation (c.188G>A/p.Arg63Gln) was identified in the ACTG2 gene, and the diagnosis of Berdon's syndrome was obtained." (PMID 33859849, 2021).
bladder cancer (2 papers, 2022 to 2025). "We developed a Risk Score model that was related to the overall survival of bladder cancer patients based on doxorubicin-target HRGs: ACTG2, MYC, PDGFRB, DHRS2, and KLRD1." (PMID 38806990, 2025). "ACTG2 can also affect hepatocellular carcinoma cell migration and tumor metastasis, and MYH11 may play a pivotal function in the progression of lung cancer and bladder cancer." (PMID 35768705, 2022).
megacystis-microcolon-intestinal hypoperistalsis syndrome (2 papers, 2017 to 2025). "Two patients had a genetically confirmed diagnosis of megacystis microcolon intestinal hypoperistalsis syndrome (MMIHS), by the presence of the enteric smooth muscle actin gamma 2 (ACTG2) mutation." (PMID 40249397, 2025).
prostate carcinoma (2 papers, 2017 to 2021). A carcinoma that arises from epithelial cells of the prostate gland. "Importantly for six of the eight candidates, (TRIB1, PCA3, GRHL2, ACTG2, GSN, and MXI1) we were able to confirm the differential expression of the genes that harbor these STRs using a large dataset of prostate cancers compared to adjacent non-malignant cells." (PMID 29203868, 2017).
cholelithiasis (1 paper, 2025). The presence of crystallized deposits forming in the gallbladder or biliary tree, primarily composed of cholesterol, bilirubin, and bile. "The other ACTG2 variants (R63Q, R178C, R257H, and R257C) found in our cohort were significantly more likely to be associated with the need for decompression stomata (100%), parenteral nutrition (100%), and hepatobiliary complications (IFALD, 72.2%; cholelithiasis, 81.8%) than R40H and/or P39R." (PMID 41387873, 2025).
coccidiosis (1 paper, 2024). A parasitic infection caused by Coccidia. "Calves with coccidiosis had higher TFF-3 levels and ACTG2 after treatment (72nd hours) compared to the control group." (PMID 39628866, 2024).
endometrial polyp (1 paper, 2024). A benign nodular lesion protruding above the surface of the endometrium. "Relevant critical genes were downregulated in endometrial polyps, including ACTA2, KCNMB1, KCNMB2, PPP1R12B, MYL9, and ACTG2." (PMID 38473810, 2024).
fibrosis (1 paper, 2024). the formation of excess fibrous connective tissue in an organ or tissue in a reparative or reactive process. "Finally, the disease gene-association analysis on the DEGs without the respiratory tract disease filter showed that six DEGs (namely, ACTG2, AGER, COL1A1, COL3A1, IGF1, and SPP1) were associated with fibrosis." (PMID 39944354, 2024).
ileus (1 paper, 2023). Decrease in peristalsis in the absence of a mechanical bowel obstruction. "This does not exclude completely that ACTG2 variants could contribute to milder gastrointestinal phenotypes such as malabsorption and ileus, and further work in less severe disease cohorts is warranted." (PMID 37288276, 2023).
intestinal pseudo-obstruction (1 paper, 2014). A type of ILEUS, a functional not mechanical obstruction of the INTESTINES. "We also found some of the same heterozygous mutations that we observed as apparent de novo mutations in MMIHS segregating in families with intestinal pseudo-obstruction, suggesting that ACTG2 is responsible for a spectrum of smooth muscle disease." (PMID 24676022, 2014). "Identification of ACTG2 mutations underlying a significant proportion of MMIHS and intestinal pseudo-obstruction has significance for three major reasons." (PMID 24676022, 2014).
invasive breast carcinoma (1 paper, 2020). A carcinoma that infiltrates the breast parenchyma. "The gene expressions of ACOT7, STAT1, TYMP, and VOPP1 were significantly increased in invasive breast carcinoma, while the gene expressions of ACTG2, CNN1, CDC14B, NFIB, RCN1, and TRIM2 were dramatically downregulated in BRCA." (PMID 31986487, 2020).
ischemia reperfusion injury (1 paper, 2024). Adverse functional, metabolic, or structural changes in ischemic tissues resulting from the restoration of blood flow to the tissue (reperfusion), including swelling; hemorrhage; necrosis; and damage from free radicals. "Furthermore, intestinal damage from ischemia reperfusion injury leads to increased serum concentration of ACTG2 in rats." (PMID 39272260, 2024).
liver cancer (1 paper, 2024). An epithelial or non-epithelial malignant neoplasm that arises from the liver. "Abnormal expression of ACTG2 has been found in many cancers, such as ACTG2 involved in cell migration and distant metastasis in liver cancer." (PMID 38829766, 2024).
melanoma (1 paper, 2025). A malignant, usually aggressive tumor composed of atypical, neoplastic melanocytes. "CAFs isolated from melanoma (MELF) with low activity of ACTG2 exhibited distinct signals for both types of smooth muscle actins αSMA and γSMA under in vitro conditions." (PMID 40971055, 2025).
prune belly syndrome (1 paper, 2023). "Patient 11, with a Prune Belly syndrome phenotype, had a MYH11 likely benign allele in addition to the identified ACTG2 VUS allele c.850A > G; p.(Met284Val) which is insufficient evidence to solve this case." (PMID 37288276, 2023).
renal failure (1 paper, 2024). "PBS, an ACTG2 (actin gamma 2) visceral myopathy, is a highly morbid condition as the severe form is associated with stillbirth, renal failure, urinary infections, and pulmonary hypoplasia." (PMID 38895052, 2024).
sporotrichosis (1 paper, 2024). The commonest and least serious of the deep mycoses, characterized by nodular lesions of the cutaneous and subcutaneous tissues. "The results showed that compared with the control group, the expressions of DKK1 and ACTG2 were significantly downregulated while the expressions of JAK3 and SLC7A11 were significantly upregulated in the tissues of the sporotrichosis patients, consistent with the sequencing data." (PMID 38172590, 2024).
thymoma (1 paper, 2021). A neoplasm arising from the epithelial cells of the thymus. "This study identified key genes related to the prognosis of thymoma, including LIPE, MYH6, ACTG2, KLF4, SULT4A1, and TF." (PMID 34104648, 2021). "By screening the DEGs that had a significant impact on the prognosis of thymoma, we identified LIPE, MYH6, ACTG2, KLF4, SULT4A1, and TF as key genes." (PMID 34104648, 2021). "LIPE, MYH6, ACTG2, KLF4, SULT4A1, and TF were the key genes affecting the prognosis of thymoma." (PMID 34104648, 2021). "ACTG2, KLF4, SULT4A1, and TF were all involved in the occurrence or development of cancer, but their biological significance in thymoma was not clear." (PMID 34104648, 2021).
cancer (14 papers, 2014 to 2025). A tumor composed of atypical neoplastic, often pleomorphic cells that invade other tissues. "ACTG2 and microRNA-145 (miR-145) are aberrantly expressed in other cancers and ACTG2 can be induced by miR-145." (PMID 27107594, 2016). "Furthermore, microRNA-145 (miR-145) can positively regulate expression of ACTG2, and overexpression of this microRNA inhibits cell proliferation, cell invasion, tumor growth and can induce apoptosis in other cancer cell types." (PMID 27107594, 2016). "ACTG2, EZR, CNN1, DES, MS4A12 and NTN1 are all expressed at significantly higher levels in normal tissue compared to adenomatous polyp or carcinoma tissues." (PMID 25423035, 2014).
tumor (11 papers, 2007 to 2025). "In addition to carrying the Braf gene, chromosome 6 carries several genes that are highly expressed in the LNM and tumor populations (Aqp1, Col1a2, Cav1, Cav2, Ptn, RaRes2, Fkbp9, Actg2, Ybx3, Mgp, Sox5, Kcna1, and Ptms)." (PMID 40571713, 2025). "Interestingly, eight primary tumors and two lymph node metastases displayed positive staining for ACTG2 in tumor cells, albeit at variable level and appearance." (PMID 27107594, 2016). "Induction of ACTG2 at some point during primary tumor growth may have beneficial effects as ACTG2 showed growth inhibitory effects, at least in vitro." (PMID 27107594, 2016). "We could not detect ACTG2 expression in the enterochromaffin cells of the normal intestinal mucosa, suggesting that expression of ACTG2 can be induced at some point during tumor progression representing a dedifferentiated phenotype, rather than being normally expressed in this cell type." (PMID 27107594, 2016). "Differential expression analysis of the metastatic and primary tumor samples shows that a large number of the most highly downregulated genes such as TAGLN, ACTG2, TPM1, MYH111 and DES have been previously identified as expressed mostly in the prostatic stromal cells." (PMID 17430594, 2007).
myopathy (3 papers, 2021 to 2025). A disease of the muscle in which the muscle fibers do not function properly. "Alternatively, one could speculate that the constipation and mild ventricular dysfunction seen in NAA80 individuals reflect a minor ACTG2 and ACTC1 dysfunction, in a similar way as the mild myopathy of NAA80 individuals reflects a minor form of the severe, lethal myopathy seen in ACTA1 individuals." (PMID 34805998, 2021).
intestinal diseases (2 papers, 2017 to 2020). "Our bioinformatic alignment and calculation on pathogenic proteins for intestinal diseases predicted that MSTO1 indeed shows a close relationship with ACTG2." (PMID 29255146, 2017).
gastrointestinal disorders (1 paper, 2023). "As confirmatory evidence, ACTG2 was also recently identified as the most strongly associated gene in patients with gastrointestinal disorders using a Bayesian genetic association method." (PMID 37288276, 2023).
infection (1 paper, 2013). The state of being infected such as from the introduction of a foreign agent such as serum, vaccine, antigenic substance or organism. "The fact that angiopoietin is known to limit the formation of actin stress fibres correlates well with our findings that at 48 h post infection transcription of ANGPTL4 further increased and transcription of gamma actin (ACTG1 and ACTG2) declined." (PMID 23326599, 2013).
ACTG2 also shares sentences with these, for which no sentence is quoted: colon cancer (2 papers); neuropathy (2); asthma (1); cholecystolithiasis (1); chronic atrial and intestinal dysrhythmia (1); depression (1); Desminopathy (1); dilated cardiomyopathy (1); hemangioma (1); hepatocellular carcinoma (1); hydronephrosis (1); Hydroureter (1); lung carcinoma (1); lymphatic disease (1); mitochondrial disease (1); multisystemic smooth muscle dysfunction syndrome (1); neuroendocrine tumor (1); polyp (1); prostate tumors (1); psychiatric disorder (1); sarcoma (1); schizophrenia (1); viral myocarditis (1).